ATP1A2 (ATPase Na+/K+ transporting subunit alpha 2)
Diseases named in the same sentence as ATP1A2 in open-access papers (continued):
Sharing a sentence is not in itself a finding about the gene and the disease.
breast tumors (1 paper, 2022). "Interestingly, ATP1A1 and ATP1B1 isoforms were overexpressed in breast tumors while ATP1A2 was downregulated in breast tumors and ATP1B3 mRNA expression was unchanged." (PMID 36232400, 2022). "Among them, we found that ATP1A1, ATP1A2, ATP1B1, and ATP1B3 are highly expressed in normal breast tissue and among them, ATP1A1 and ATP1B1 are upregulated in breast tumors while ATP1A2 is downregulated and ATP1B3 is unchanged." (PMID 36232400, 2022).
colorectal cancer (1 paper, 2023). A primary or metastatic malignant neoplasm that affects the colon or rectum. "With the exception of ATP1A2, the remaining genes were found to influence the development of colorectal cancer." (PMID 38681779, 2023).
Dravet syndrome (1 paper, 2025). "Similarly, mutations in ATP1A2 (responsible for FHM2) and SCN1A (associated with Dravet syndrome and other epileptic syndromes) disrupt potassium and sodium channel function, respectively, lowering thresholds for both CSD and epileptiform activity." (PMID 40949139, 2025).
ductal carcinomas (1 paper, 2007). "In particular, transcription regulators (ATF3, PIGR), genes encoding proteins with cytokine and growth factor activity (PTN, CX3CL1) and genes encoding proteins involved in ion transport and metabolism (ATP1A2, MMP7) were downregulated in ductal carcinomas when compared with normal cells." (PMID 17389037, 2007).
familial hemiplegic migraine 2 (1 paper, 2021). "It has been shown in familial hemiplegic migraine 2 (FHM2), a rare subtype of migraine with aura, that mutations in the expression of Atp1a2 cause ‘loss of function’ of the Na+/K+ ATPase pump in astrocytes, therefore affecting glutamate clearance." (PMID 34069553, 2021).
fibromyalgia (1 paper, 2025). A chronic disorder of unknown etiology characterized by pain, stiffness, and tenderness in the muscles of neck, shoulders, back, hips, arms, and legs. "LMX1B mutations linked to nail-patella syndrome (NPS) may also contribute to chronic pain, suggesting heightened pain sensitivity; ATP1A2 helps regulate metabolism by maintaining ion gradients across cell membranes and is linked to pain disorders such as neuropathic pain and fibromyalgia." (PMID 40313396, 2025).
gastrointestinal stromal tumor (1 paper, 2022). "Furthermore, the results revealed that two of the four central DEGs (ATP1A2, PLN, KCNMA1, and SCNN1B) of the PPI network were created in this module, thus suggesting that PLN and ATP1A1 may have a significant important role in gastrointestinal stromal tumors." (PMID 35655923, 2022).
infantile-onset epilepsy (1 paper, 2019). Epilepsy starting in the first 12 months of life, including self-limiting and refractory seizures, and epilepsies with and without developmental disorders. "Additional infantile-onset epilepsy patients linked with ATP1A2 and ATP1A3 are found in the literature." (PMID 31572294, 2019).
Leukoencephalopathy (1 paper, 2020). This term describes abnormality of the white matter of the cerebrum resulting from damage to the myelin sheaths of nerve cells. "Other genetic mutations known to be associated with similar clinically presenting diseases (FHM1 in CACNA1A, FHM2 in ATP1A2, and mutations within COL4A1 cause COL4A1-associated leukoencephalopathy) have been identified through follow-up testing requested by clinicians." (PMID 31915071, 2020).
lymphoma (1 paper, 2022). A malignant (clonal) proliferation of B- lymphocytes or T- lymphocytes which involves the lymph nodes, bone marrow and/or extranodal sites. "Chaetocin treated cells showed downregulation of potassium and sodium transporters (ATP1A2), eventually leading to a reduction of K+ and accumulation of Na+, which have been associated with apoptosis in lymphoma cells." (PMID 34996497, 2022).
melanoma (1 paper, 2016). A malignant, usually aggressive tumor composed of atypical, neoplastic melanocytes. "By microarray analysis we detected little or no expression of ATP1A2, ATP1A3 or ATP1A4 in xenografted melanomas or in normal human melanocytes." (PMID 27545456, 2016).
motor neuron disease (1 paper, 2023). "Thus, to achieve at least 50% target reduction with minimal toxicity, we proceeded with two independent Atp1a2 targeting ASOs, ASO1 at 50μg and ASO3 at 25μg, to characterize effects of Atp1a2 knockdown in motor neuron disease in SOD1*G93A animals." (PMID 38015828, 2023). "Our results uncouple SOD1 aggregation and disease course and show that downregulation of Atp1a2 by ASOs before disease onset fails to slow motor neuron disease in mutant SOD1 mice." (PMID 38015828, 2023).
ovarian carcinoma (1 paper, 2024). A malignant neoplasm originating from the surface ovarian epithelium. "ATP1A2 has been shown to be highly expressed in platinum-resistant ovarian cancer." (PMID 39684755, 2024).
respiratory failure (1 paper, 2023). The significant impairment of gas exchange within the lungs resulting in hypoxia, hypercarbia, or both, to the extent that organ tissue perfusion is severely compromised. "Notably, ZFHX, Dbx1, ATP1a2, Tshz, Jmjd3, and Vglut2 have been implicated in causing respiratory failure or death." (PMID 38179140, 2023).
tumor (13 papers, 2011 to 2026). "Moreover, primary tumor outcome, residual tumor, ATP1A2, ATP1A3, and ATP1A4 were closely related to the risk of recurrence and mortality in OSC." (PMID 32684846, 2020). "Specifically, stk11 encodes a serine/threonine kinase involved in cellular polarity and tumor suppression, while atp1a2 has been shown to inhibit tumor growth in vivo." (PMID 40941396, 2025). "Multivariate analysis showed that primary therapy outcome (p < 0.001), residual tumor (p = 0.004), ATP1A2 (p = 0.006), ATP1A3 (p < 0.001), and ATP1A4 (p < 0.001) were independent risk factors for OS." (PMID 32684846, 2020). "ATP1A1 and ATP1A3 were highly expressed in tumor tissues, whereas ATP1A2 and ATP1A4 were highly expressed in normal tissues (all p < 0.001)." (PMID 32684846, 2020). "Based on the results of multivariate analysis, a genomic-clinical nomogram, including primary tumor therapy outcome, residual tumor, ATP1A2, ATP1A3, and ATP1A4, was established to predict the 1-, 3-, and 5-year OS and DSS in patients with OC." (PMID 32684846, 2020). "ATP1A2 inhibits the proliferation, invasion, migration, and epithelial–mesenchymal transition of prostate cancer cells by regulating the transforming growth factor-β/Smad signaling pathway, which exerts tumor-suppressing effects." (PMID 41533486, 2026). "Conversely, the expression of ATP1A2 and ATP1A4 was higher in normal ovarian tissues than in tumor tissues, and the high expression of ATP1A4 in OSC tissues was significantly correlated with prolonged OS and DSS." (PMID 32684846, 2020). "First, when comparing the differential expression of ATP1A2 and ATP1A3 in tumor and normal tissues, it was found that the results from the TCGA and ICGC databases were contradictory." (PMID 32684846, 2020). "CX3CL1, AGT, ATP1A2, and IGSF1 mRNAs proved to be significantly down-modulated in the BM-infiltrating GD2 positive fractions compared to primary tumor cells (P<0.0001, P = 0.0325, P = 0.0196, P = 0.0047, respectively)." (PMID 22253825, 2012). "Compared to primary tumor cells, BM-infiltrating NB cells down-modulated the expression of CX3CL1, AGT, ATP1A2 mRNAs, whereas they up-regulated several genes commonly expressed by various lineages of BM resident cells." (PMID 22253825, 2012). "Conversely, the expression of ATP1A2 and ATP1A4 was lower in most tumor cell lines." (PMID 32684846, 2020). "On the contrary, women with ERα-positive BC have a significantly higher survival probability when the tumor expresses high levels of ATP1A1 or ATP1B1 while no significant changes in RFS of women with ERα-positive BC have been evidenced considering the ATP1A2 mRNA expression." (PMID 36232400, 2022).
neurological disorders (8 papers, 2016 to 2025). "This is also reflected in the expressive relationship between the α1, α2, and α3 isoforms in the CNS and the complex neurological disorders caused by mutations in the ATP1A2 and ATP1A3 genes." (PMID 27199775, 2016). "However, severe neurological disorders have been associated with variants in the ATP1A2 and ATP1A3 genes encoding the α2 and α3 subunit isoforms." (PMID 28620085, 2017). "Sporadic or inherited mutations in ATP1A2 and ATP1A3 have been identified and associated with various neurologic disorders." (PMID 33544780, 2021). "A close relationship between glutamate signalling, ROS, and ATP1A2/ATPA3-related neurological disorders has also been suggested." (PMID 33544780, 2021). "Genetic mutations in the ATP1A2 gene and ATP1A3 gene, encoding the α2 and α3 subunit isoforms, respectively can cause distinct neurological disorders, concurrent to impaired NKA activity." (PMID 27313535, 2016). "We propose that decreases in ASC levels may affect neural network development and are linked to the pathophysiology of ATP1A2- and ATP1A3-related neurologic disorders." (PMID 33544780, 2021). "Therefore, it is likely that decreased levels of ASC may contribute to the symptomatic manifestation of ATP1A2/ATP1A3-related neurologic disorders." (PMID 33544780, 2021). "Notably, the onset of symptoms in ATP1A2- and ATP1A3-related neurologic disorders is usually triggered by physiological or psychological stressors." (PMID 33544780, 2021).
cancer (4 papers, 2020 to 2026). A tumor composed of atypical neoplastic, often pleomorphic cells that invade other tissues. "ATP1A2, which is highly expressed in many cancer types, shows potential as a therapeutic target." (PMID 41533486, 2026). "However, in the context of cancer-related scenarios, whether ATP1A2 is involved in regulating classical pathways such as the PI3K/AKT and MAPK pathways has not yet been reported." (PMID 41533486, 2026). "Namely, the expression levels of ATP1A2, CILP, and THSD4 were downregulated in cancer tissues compared with paracancerous tissues, whereas the expression levels of SMYD2 and GAPDHP1 were upregulated." (PMID 35498536, 2022). "To further validate our data, we tested the protein expression of the ATP1A gene family members (including ATP1A1, ATP1A2, and ATP1A3) in cancer and paracancerous tissue samples of six patients with OSC." (PMID 32684846, 2020). "We found seven upregulated genes (MCM10, RAD51-associated protein 1 (RAD51AP1), KIF2C, Y_RNA, FAM64A, CDC6, and CDCA8) and six downregulated genes (ADAMTS8, ATP1A2, MYH1, OGN, OMD, and ZBTB16) in at least two phenotypes containing either ALT high/middle or TEL high/middle regardless the cancer type." (PMID 38763334, 2024). "In addition, quantitative real-time PCR results showed that the expression levels of ATP1A2, CILP, and THSD4 were downregulated and the expressions of SMYD2 and GAPDHP1 were upregulated in cancer tissues compared with normal tissues." (PMID 35498536, 2022).
infection (1 paper, 2025). The state of being infected such as from the introduction of a foreign agent such as serum, vaccine, antigenic substance or organism. "Nine down-regulated DEGs were commonly downregulated in response to either Aβ pathology or MA10 infection (Vegfa, Atp1a2, Slc6a11, Gja1, Slc6a11, Gpr37l1, Plpp3, Gstm1, Agt)." (PMID 41497643, 2025).
ATP1A2 also shares sentences with these, for which no sentence is quoted: migraine with aura (7 papers); benign familial infantile convulsions (3); cerebellar ataxia (3); generalized epilepsy (3); Parkinsonism (3); alternating hemiplegia of childhood 1 (2); Areflexia (2); Coma (2); depression (2); developmental and epileptic encephalopathy (2); developmental delay (2); diabetes (2); epileptic encephalopathies (2); episodic ataxia (2); hydrops fetalis (2); optic atrophy (2); polymicrogyria (2); psychiatric disorder (2); Rapid-onset dystonia-parkinsonism (2); sensorineural hearing loss (2); Vertigo (2); abdominal aortic aneurysm (1); adenoma (1); Alzheimer disease (1); amyotrophic lateral sclerosis (1); aortic aneurysm (1); arthrogryposis (1); autosomal dominant inheritance disorder (1); biotinidase deficiency (1); breast invasive carcinoma (1).
A further 51 diseases each share a sentence with ATP1A2 in 1 paper.